ERRFI1 (ERBB receptor feedback inhibitor 1)
Diseases named in the same sentence as ERRFI1 in open-access papers (continued):
Sharing a sentence is not in itself a finding about the gene and the disease.
tumor (54 papers, 2007 to 2026). "Given that ERRFI1 is associated with tumor development and drug resistance, we further explored the functional role of ERRFI1 in EGFR feedback activation in the context of MRTX1133." (PMID 37020035, 2023). "For example, only the occipital tumor region showed amplification of the EGFR locus, whereas a PTPN11 missense mutation and ERRFI1 homozygous deletion were exclusively in the parietal tumor region." (PMID 36114166, 2022). "Such allele specific expression of the mutated allele from the same tissue specimen suggests nearly complete loss of function of ERRFI1 in this patient's tumor." (PMID 24550739, 2014). "The tyrosine kinase inhibitor gefitinib has demonstrated anti-tumor activity in mice in spontaneous tumors driven by ERRFI1 germline loss." (PMID 24550739, 2014). "To investigate the clinical relevance and potential role of MIG6 in tumor progression, we cataloged ERRFI1 mutations in patient samples by analyzing publicly available data sets, including The Cancer Genome Atlas (TCGA) and Catalogue of Somatic Mutations in Cancer (COSMIC)." (PMID 39129344, 2025). "LC-C may promote radiation induced anti-tumor effect by increasing the expressions of ERRFI1 and associated with EGFR and STAT3 signaling pathways." (PMID 33869036, 2021). "A nonsynonymous DNA mutation was also identified in tumour 25R9 (intact 1p) in the ERRFI1 gene." (PMID 17940511, 2007). "Mitogen-inducible gene 6 (MIG6) is encoded by the gene, ERRFI1, with its function being a well-characterized epidermal growth factor receptor (EGFR) inhibitor and tumor suppressor." (PMID 40378957, 2025). "In this study, ERRFI1 is negatively correlated with prognosis and holds potential as a target for tumor immunotherapy, warranting further investigation." (PMID 40308576, 2025). "As a tumor suppressor, ERRFI1 directly interacts with EGFR to inhibit its activation, thereby suppressing tumor cell proliferation and metastasis." (PMID 40308576, 2025). "Under EGFR mutation conditions and prolonged exposure to EGFR‐TKIs, phosphorylated ERRFI1 ceases to operate as a tumor suppressor; instead, it actively promotes the survival of cancer cells." (PMID 39096122, 2024). "ERBB receptor feedback inhibitor 1(ERRFI1) was known as a tumor suppressor, and initiates cell growth by directly inhibiting the epidermal growth factor receptor and its downstream pathway." (PMID 36524001, 2022). "ERRFI1 was located on chromosome 1p36 in humans and a locus that has long been thought to contain many putative tumor suppressor genes, and was frequently altered in many cancers including HCC." (PMID 36359865, 2022). "ERRFI1 is a tumor suppressor in tumor cells in situ, and its expression is required to prevent apoptosis and BC cell metastasis." (PMID 35859293, 2022). "AKAP12, another ERK1/2 inhibitor, was found preferentially upregulated in FGFR tumors, whereas RALT/ERRFI1, an EGFR inhibitor and degradation promoter, was strongly overexpressed only in the F2T2↑ tumor, explaining its paradoxical EGFR expression loss." (PMID 33853673, 2021). "In human samples, EGFR-positive HCC tissues and their corresponding non-tumor tissues exhibited decreased ERRFI1 mRNA expression." (PMID 33806040, 2021). "It is reported that ERRFI1 decreases tumor formation by inhibiting cell proliferation and increasing apoptosis." (PMID 34608122, 2021). "Recently, tamoxifen-resistant breast cancer cell lines treated with OGT small molecule inhibitor OSMI-1 showed anti-tumor activity via epigenetic activation of the tumor-suppressor ERRFI1." (PMID 34771527, 2021). "Expression studies have shown that ERRFI1 is downregulated in several human tumor types and BCa cell lines." (PMID 32432675, 2020). "Previous studies identified high EGFR expression promote tumor progression, and high ERRFI1 expression can slow tumor progression." (PMID 32984316, 2020).
tumor (continued). "To improve our understanding of TNBC biology and expand the limited knowledge on the effects of GCs on BCa and the characteristic tumor-suppressive properties of ERRFI1, we sought to investigate the GC-ERRFI1 regulatory axis in the context of TNBC." (PMID 32432675, 2020). "In summary, we show that tamoxifen-resistance is associated with sensitivity to OSMI-1, and propose that this is explained in part through an epigenetic activation of the tumor-suppressor ERRFI1 in response to OSMI-1 treatment." (PMID 33046784, 2020). "Of the six patients analyzed with TSPG, five exhibited perturbations greater than one standard deviation in the tumor-downregulated direction for this ERRFI1 gene." (PMID 33205131, 2020). "One such study has reported that up-regulated ERRFI1 expression is capable of attenuating tumor cell migration." (PMID 33117083, 2020). "In the highly metastatic TNBC model MDA-MB-231, ERRFI1 lost its tumor suppressive capacity and instead conferred pro-tumorigenic effects." (PMID 32432675, 2020). "Tumor samples from high-risk group A showed a higher mean overall IHC score for Anti-MSX1, Anti-CD271, Anti-ERRFI1, Anti-PTPRF, Anti-TNFRSF21, Anti-TNFRSF12a, and Anti-IGFBP2, but without significance." (PMID 30641895, 2019). "ERRFI1 is known as a tumor suppressor by directly inhibiting the epidermal-growth-factor-receptor and, therefore, its downstream pathways initializing cell growth." (PMID 30641895, 2019). "Signal attenuation and downregulation of RTK pathways provide important implications in cancer therapeutics and several well characterized negative regulators in RTK signaling (such as PTEN, LRIG1 and ERRFI1) are bona fide tumor suppressors." (PMID 29455648, 2018). "Genetic studies in the mouse have pointed to an essential role of Errfi1 in restraining Egfr‐dependent cell proliferation in normal tissues as well as suppressing Egfr‐driven tumor formation." (PMID 30021798, 2018). "Tumor FR2048T displayed a translocation placing CCNE1 downstream the first untranslated exon of the highly expressed ERRFI1 gene, leading to a highly expressed ERRFI1-CCNE1 fusion." (PMID 30531861, 2018). "MIG6 tumor suppressive role is supported by the finding that upon deletion of ERRFI1, mice frequently develop spontaneous or chemical-induced tumors." (PMID 26788993, 2016). "Rapid and robust disease regression was noted in this ERRFI1 inactivated tumor when treated with erlotinib, an EGFR kinase inhibitor." (PMID 24550739, 2014). "Also in the context of cancer, exosomal miR-148a-3p was shown to promote tumor angiogenesis through activation of the EGFR/MAPK signaling pathway by ERRFI1 inhibition." (PMID 39120274, 2024). "The tumor suppressor activity of the Gene 33 (Mig6, ERRFI1) has been confirmed in LC." (PMID 35620343, 2022). "ERRFI1 is involved in the induction of cellular senescence and tumor suppressor events." (PMID 35859293, 2022). "ERRFI1 is considered a tumor suppressor that directly inhibits epidermal growth factor receptors." (PMID 35480093, 2022). "In addition, the immunohistochemistry staining showed that ERRFI1 was significantly downregulated in HCC samples compared to para-tumor tissues." (PMID 34608122, 2021). "In addition, in vivo experiments were performed to study the regulatory role of exosomal miR-148a-3p in the ERRFI1/EGFR/MAPK axis affecting tumor formation and angiogenesis in nude mice." (PMID 33117083, 2020). "Furthermore, five exhibited perturbations greater than one standard deviation in the tumor-downregulated direction for the ERRFI1 gene." (PMID 33205131, 2020). "ERRFI1 is a tumor suppressor of various receptors in the Ras pathway." (PMID 29617658, 2018). "There has also been evidence that ERRFI1 acts as a tumor-suppressor gene." (PMID 29801473, 2018). "A mutation hotspot was found downstream of ERRFI1, an important regulator of the EGFR pathway, which may serve as a potential tumor suppressor." (PMID 28358873, 2017).
tumor (continued). "Similarly, rapid and robust disease regression was noted in the patient with an ERRFI1 mutant tumor when treated with erlotinib, an EGFR kinase inhibitor." (PMID 24550739, 2014). "Elevated tyrosine phosphorylation of Errfi1 characterised HER2 tumours." (PMID 25200860, 2014). "This may reflect different functions, depending on tumour type, but it could also indicate that more advanced stage tumours grow more rapidly since ERRFI1 expression can be induced by a variety of stimuli such as growth factors, hypoxia and stress factors." (PMID 17940511, 2007). "Furthermore, in vivo experiments demonstrated that the loss of ERRFI1, a pivotal gene within the STING signature, significantly enhanced antitumor immunity and exhibited a synergistic effect with α-PD1 therapy to promote tumor control." (PMID 40308576, 2025). "Indeed, Errfi1-null mice develop neoplasms in multiple tissues." (PMID 34206547, 2021). "ERBB receptor feedback inhibitor 1 (ERRFI; also known as mitogen-inducible gene 6 protein), e.g., which encodes a cytosolic protein that directly binds and inhibits ErbB-family receptors, is deleted in cancer and has shown tumor suppressor activity in experimental cancer models." (PMID 29229958, 2017). "Importantly, phosphorylation of Errfi1 on Y394 reduces its ability to inhibit Egfr, indicating that this modification may act to attenuate negative regulation of HER2 signalling by Errfi1 in these tumours." (PMID 25200860, 2014). "ERRFI1 functions as a regulator of EGFR-mediated signaling and is involved in tumor development and chemoresistance in CRC." (PMID 39905540, 2025). "The results show that BRAF, CDKN1A, DIABLO, PEA15, ERRFI1, and RPS6KB1 are highly expressed in tumor cell lines, which is the same as in the TCGA database." (PMID 39239554, 2024). "Four candidate tumor suppressor genes RUNX3 (RUNX family transcription factor 3), ARID1A, ERRFI1 (ERBB receptor feedback inhibitor 1), and mTOR, are all located in the 1pter region and are involved in transcription and cell-cycle control." (PMID 39199659, 2024). "Single-cell analysis dissected that ERRFI1, ETS1, NDRG1, and ZMAT3 were expressed in the tumor microenvironment." (PMID 37600707, 2023). "The results showed that the transcriptional expression levels of NDRG1 (P < 0.001), ERRFI1 (P < 0.001), IRS2 (P < 0.001), IGFBP4 (P < 0.01), and BIRC3 (P < 0.01) were significantly decreased in tumor tissues, while SOCS1 (P < 0.05) expression was increased." (PMID 35859293, 2022). "Analysis of their expression levels in tumor patients and normal subjects identified five core prognostic markers, which were EIF4EBP1, BCL2A1, NDRG1, ERRFI1 and BRD4." (PMID 36524001, 2022). "ERRFI1 expression was specifically and strongly (16-fold) upregulated in the LMS4/F2T2↑ tumor, explaining the downregulation of EGFR in this tumor in the absence of significant mRNA expression change." (PMID 33853673, 2021). "The tumor suppressive function of ERRFI1 in MDA-MB-468 is further supported by the decrease in cell survival and proliferation when Errfi1 is overexpressed." (PMID 32432675, 2020). "ERRFI1 has a role as a negative regulator of EGFR dependent skin morphogenesis, uterine steroid hormone responsiveness and as a tumor suppressor gene." (PMID 24550739, 2014). "Only the expressions of ERRFI1, ETS1, NDRG1, and ZMAT3 were detected in the tumor microenvironment." (PMID 37600707, 2023). "Among the downregulated genes were DUSP6 (Dual Specificity Phosphatase 6), a key negative regulator of ERK, and ERRFI1 (ERBB Receptor Feedback Inhibitor 1, also called Mig-6), a tumor suppressor that curbs activation of EGFR and sustained signaling through the ERK pathway." (PMID 37020037, 2023). "ERRFI1 overexpression has been shown to reduce proliferation in GBM cells by binding EGFR to Syntaxin-8 and targeting internalized EGFR to late endosomes for degradation, while knockdown of ERRFI1 expression resulted in increased tumor invasion." (PMID 36231068, 2022).
tumor (continued). "In addition, GR-positive non-tumor liver tissues featured lower EGFR expression and higher ERRFI1 mRNA expression than GR-negative tissues." (PMID 33806040, 2021). "Mechanistically, HNK accelerated the nuclear translocation of glucocorticoid receptor (GR) and promoted mitogen-inducible gene 6 (MIG6)/ERBB receptor feedback inhibitor 1 (ERRFI1) expression, leading to EGFR degradation and thereby resulting in robust tumor suppression." (PMID 33806040, 2021). "For instance, the direct interaction between ERRFI1 and GRB2 may preclude activation of the mitogen-activated protein kinase pathway and confer tumor suppressive effects." (PMID 32432675, 2020). "ERRFI1 directly interacts with four members of the ERBB family and works as a negative feedback regulator of the ERBB RTK pathway by acting as a negative regulator of skin morphogenesis and tumor formation." (PMID 29801473, 2018). "ERRFI1 is a candidate tumor suppressor which functions in normal cells as a negative regulator of EGFR and the ErbB family." (PMID 21113414, 2010). "However, in a mouse model of LUAC driven by mutant EGFR, the absence of ERRFI1 accelerates both the onset and progression of the tumour." (PMID 39096122, 2024). "Furthermore, uterus-specific double knockout of Pten and Errfi1 produced a synergistic effect on endometrial tumorigenesis, suggesting a tumor-suppressive mechanism of Gene 33 that is independent of the PTEN-mediated pathway in endometrial tumors." (PMID 34206547, 2021). "The tumor suppressors genes such as EFNA1 (Ephrin-A1), ERRFI1 (ERBB Receptor Feedback Inhibitor 1), LATS2 (Large Tumor Suppressor Kinase 2) and PLK2 (Polo-Like Kinase 2) also show higher average expression in PD0325901 resistant cell lines and thus may be contributing to PD0325901 resistance." (PMID 27030518, 2016). "EGFR-positive non-tumor tissues exhibited significantly lower ERRFI1 expression than EGFR-positive HCC and non-tumor tissues." (PMID 33806040, 2021). "Furthermore, overexpression of an SNV in ERRFI1 (E384X), a negative regulator of EGFR, was detected in a non-FGFR2 translocation patient's tumor." (PMID 24550739, 2014). "This implies that the tumor-suppressive function of ERRFI1 can no longer effectively mitigate the pro-tumorigenic effects of CORT in metastatic BCa and may be attributed to the impaired CORT-mediated induction of ERRFI1 in this cell line." (PMID 32432675, 2020).
cancer (33 papers, 2016 to 2026). A tumor composed of atypical neoplastic, often pleomorphic cells that invade other tissues. "Nonsense mutation at glutamic acid 384, within the segment 2 of the EGFR and c-Abl binding motif of ERRFI1, exists in sporadic intrahepatic cholangiocarcinoma and is associated with enhanced cancer regression upon EGFR inhibition." (PMID 34206547, 2021). "Notably, it has been reported that upregulation of ERRFI1 is associated with acquired resistance to the EGFR tyrosine kinase inhibitor (TKI) in a cancer cell line." (PMID 31969149, 2020). "Mitogen-inducible gene-6 (Mig-6; also known as RALT, Errfi1 and Gene-33) encodes a cytosolic adaptor protein that is evolutionarily conserved in vertebrates and is implicated in suppression of tumorigenesis, cancer progression, and metastasis." (PMID 27341132, 2016). "ERRFI1, encoding the epidermal growth factor receptor (EGFR) inhibitor MIG6, is mutated in various cancers, including BTC, representing a potential predictive biomarker." (PMID 42234947, 2026). "We propose that the mutation status of ERRFI1 and the expression levels of MIG6 can serve as additional biomarkers for guiding EGFR‐targeted cancer therapies, including glioblastoma." (PMID 39129344, 2025). "In humans, ERRFI1 is located in chromosome 1p36, a locus long believed to contain multiple putative tumor suppressor genes and frequently altered in many cancers." (PMID 34206547, 2021). "ERRFI1 is a tumor suppressor gene, and low ERRFI1 expression has been observed in various types of cancer." (PMID 33869036, 2021). "The ERRFI1 gene locus is on chromosome 1p36, a segment of chromosome where many cancer-related genes are located." (PMID 33869036, 2021). "In complementary cellular assays on cancer hallmarks, we found that ERRFI1 restricts the pro-tumorigenic effect of CORT in the normal breast epithelial model MCF10A and to a lesser degree in the metastatic TNBC line MDA-MB-468." (PMID 32432675, 2020). "In human tissues, ERRFI1 expression is downregulated in various cancers and in skin with chronic inflammation, supporting a role for negative regulation of cell proliferation." (PMID 31969149, 2020). "Given that ERRFI1 functions a negative feedback inhibitor of EGFR signaling, we presumed that the function of the GC-ERRFI1 regulatory axis on different cancer hallmarks will be highlighted in this cell line." (PMID 32432675, 2020). "In a recent study, it was discovered that the down-regulation of ERRFI1 enhances resistance to MEK inhibition in KRAS mutant cancer cells." (PMID 29801473, 2018). "In various cancers such as skin, breast, pancreatic, and ovarian, ERRFI1 has been strongly down-regulated." (PMID 29801473, 2018). "MiRNA profiling combined with RNA‐Seq in MET‐addicted cancer cell lines led us to identify the miR‐205/ERRFI1 (ERBB receptor feedback inhibitor‐1) axis as a novel mediator of resistance to MET tyrosine kinase inhibitors (TKIs)." (PMID 30021798, 2018). "ERRFI1 is a negative regulator of EGFR family members, including EGFR, HER2 and HER3; all have been implicated in cancer." (PMID 28358873, 2017). "However, ERRFI1 inactivation contributes to the acquired resistance to targeted therapy with EGFR tyrosine kinase inhibitors in cancer cells." (PMID 39905540, 2025). "Erlotinib, primarily known for EGFR inhibition in cancer therapy, also interacts with ERRFI1." (PMID 37862243, 2023). "This may indicate that ERRFI1 is involved in protecting these cancer cells to undergo cellular senescence by SAL." (PMID 36008945, 2022). "There are 10 highly significant, direct and physical associators with a confidence score of ≥5.0 namely – RELA, HMOX2, EZH2, p-10Y-ERBB3-1, WDR1, ERRFI1, PRG2, FMR1, DEFA6-(?-100), cytf_human and the majority of the network associators of POTEE are epigenetically activated in many cancers." (PMID 34788504, 2021). "Previous studies showed that genetic mutations in the ERRFI1 coding region do not seem to be frequent in the cancers analyzed." (PMID 33869036, 2021).
cancer (continued). "In the setting of MET‐addicted cancers, our work anticipates that assessing ERRFI1 and miR‐205 expression could guide the identification of patients that develop adaptive EGFR‐driven resistance to MET‐TKIs." (PMID 30021798, 2018). "To assess AXL and MIG6 (ERRFI1) mRNA expression in NSCLC patients, we analyzed the Lee lung dataset from Oncomine and the lung cancer cell lines from the CCLE (Cancer Cell Line Encyclopedia)." (PMID 37834326, 2023). "For ERRFI1, RTN4, PHF7, SPRY4, CCND2, and RPL19, H3K36me3 and H3K79me2 enriched higher signals in normal cell lines than that in cancer cells, and the signals of H3K79me2 changed more significantly than H3K36me3 during tumorigenesis." (PMID 37426199, 2023). "Considering the involvement of ERRFI1 in the signaling of the EGFR family, its potential role in cancer draws great attention." (PMID 34608122, 2021). "Until now, the effects of ERRFI1 on PDAC have not been revealed, and its effects in other cancers suggested that it may be promising therapeutic target and biomarker." (PMID 33789615, 2021). "Furthermore, an analysis of the relationship between infiltration estimation and gene expression in gene modules revealed that T-cell CD4+ Th1 in genes ERRFI1, ZBED5, UQCRC2, ZNF146, ABHD17A, YWHAZ, and especially PLSCR4 showed a negative correlation in nearly 40 types of cancer." (PMID 38464509, 2024).